PDE6D (phosphodiesterase 6D)
Diseases named in the same sentence as PDE6D in open-access papers:
PDE6D is named in the same sentence as 28 diseases in open-access papers, as found by Europe PMC text mining. Sharing a sentence is not in itself a finding about the gene and the disease. The quoted sentences say what the papers report.
Joubert syndrome (6 papers, 2016 to 2025). Joubert syndrome (JS) is characterized by congenital malformation of the brainstem and agenesis or hypoplasia of the cerebellar vermis leading to an abnormal respiratory pattern, nystagmus, hypotonia, ataxia, and delay in achieving motor milestones. "Mutations in PDE6D are associated with Joubert Syndrome (JBTS) (OMIM #615665), a complex neuronal ciliopathy characterized by developmental cerebellar malformations and accompanying retinal degeneration." (PMID 39026984, 2024). "Mutations in PDE6D are associated with Joubert syndrome (JS), a severe syndromic neuronal ciliopathy resulting in developmental cerebellar malformations, classically diagnosed by the ‘molar tooth sign’ upon MRI." (PMID 36672247, 2023). "Mutations in PDE6D impair the function of its cognate protein, phosphodiesterase 6D (PDE6D), in prenylated protein trafficking towards the ciliary membrane, causing the human ciliopathy Joubert Syndrome (JBTS22) and retinal degeneration in mice." (PMID 36672247, 2023). "Other known interaction partners include PDE6D, a protein whose gene is associated with primary cilia function and disruption of which may cause Joubert Syndrome 22 [MIM: 615665]." (PMID 26964041, 2016). "Recent studies found that PDE6D is involved in ciliary trafficking of INPP5E, a protein linked to Joubert syndrome." (PMID 27493202, 2016). "Furthermore, we reveal that some Joubert syndrome mutations perturb INPP5E ciliary targeting, and clarify how each CLS works: (i) CLS4 recruits PDE6D, RPGR and ARL13B, (ii) CLS2-CLS3 regulate association to TULP3, ARL13B, and CEP164, and (iii) CLS1 and CLS4 cooperate in ATG16L1 binding." (PMID 36063381, 2022).
breast carcinoma (3 papers, 2013 to 2025). "The regulatory subunit gene, PDE6D, was, however, highly expressed in all four breast cancer cell lines." (PMID 24683528, 2013). "In this paper we show significant expression of PDE6B, PDE6C, and PDE6D, in human breast cancer cell lines and patients’ breast cancer tissues." (PMID 24683528, 2013). "Moreover, PDE6D was described to be strongly expressed in breast cancer and found to be a novel candidate relapse biomarker in colorectal carcinoma." (PMID 30901922, 2019). "Apart from these studies pointing to a major role of PDE6D-KRAS interaction in cancer, PDE6D has been found to be significantly expressed in human breast cancer cells and tissues and was considered to play a role in transducing the effects of light on breast cancer." (PMID 30901922, 2019).
ciliopathy (3 papers, 2016 to 2023). "Mutations in the human PDE6D gene are associated with the ciliopathy Joubert syndrome-22, which is characterised by brain abnormalities and neurologic symptoms." (PMID 33808286, 2021).
retinal degeneration (3 papers, 2020 to 2023). Degeneration of the retina. "As a consequence, loss of Pde6d results in altered electrophysiological properties of photoreceptor cells and a slowly progressing retinal degeneration." (PMID 33681987, 2021). "A common additional feature of PDE6D-associated JS is retinal degeneration." (PMID 36672247, 2023). "Therefore, we propose that UBL3 may play a role in the sorting of proteins towards the photoreceptor outer segment, further explaining the development of PDE6D-associated retinal degeneration." (PMID 36672247, 2023). "In addition, the genes encoding several prenylated proteins that are trafficked by PDE6D, including RPGR and RAB28, are also mutated in patients with non-syndromic inherited retinal degeneration." (PMID 36672247, 2023). "Consistent with Unc119 and Pde6d deficiency, Arl3 conditional knockout mice show trafficking defects of lipidated proteins including rTα, rTγ, rod PDE6 and GRK1 to outer segments in rod photoreceptors and subsequent retinal degeneration." (PMID 33681987, 2021).
retinal diseases (3 papers, 2007 to 2022). "In this study, RPGRIP1, RANBP2, NPM1, PDE6D, NPHP5, and ABCA4 genes were selected on the basis of interaction with RPGR or RPGRIP1 or their implication in related retinal diseases, and were investigated as candidate genetic modifiers of XLPRA1." (PMID 17653054, 2007).
colorectal cancer (2 papers, 2019 to 2024). A primary or metastatic malignant neoplasm that affects the colon or rectum. "The strong overexpression in HCC points out that PDE6D might further serve as a potential candidate biomarker in HCC as suggested for colorectal carcinoma." (PMID 30901922, 2019).
idiopathic pulmonary fibrosis (2 papers, 2010 to 2013). Idiopathic pulmonary fibrosis (IPF) is a nonneoplastic pulmonary disease that is characterized by the formation of scar tissue within the lungs in the absence of any known cause. "Further, it is tempting to speculate that therapeutic prevention of PDE6D down-regulation and/or PDE6D overexpression in animal models of pulmonary fibrosis may be beneficial to boost up alveolar re-epithelization and may represent a therapeutic option in IPF." (PMID 20979602, 2010).
pancreatic cancer (2 papers, 2022 to 2024). "Deltrasin, a commercially available PDE6D inhibitor, and additional derivative compounds have previously been reported to bind in PDE6D’s hydrophobic pocket and inhibit the growth of pancreatic cancer cell lines." (PMID 35422065, 2022). "Protein–protein interaction disruptor molecules that displace PDE6d from KRAS by binding to the prenyl‐binding pocket of the PDE proved to be effective in inhibiting oncogenic KRAS signaling and showed some efficacy in models of pancreatic cancer at micromolar concentrations." (PMID 39673076, 2024).
acute leukemia (1 paper, 2022). A clonal (malignant) hematopoietic disorder with an acute onset, affecting the bone marrow and the peripheral blood. "The results presented here provide evidence of the importance of PDE6D in sustaining downstream RAS signaling and cell survival in a large panel of acute leukemia cell lines." (PMID 35422065, 2022). "Together with the fact that DW0254 compound sensitivity did not correlate with RAS mutational status alone of acute leukemia cell lines, this suggests that RAS/AKT/RAC pathway activation might be a better predictor of response to PDE6D inhibitors." (PMID 35422065, 2022).
adrenal tumor (1 paper, 2020). "Transcriptome profiling of pediatric ACTs (n = 16) and normal adrenal cortex samples (n = 6) revealed that PDE2A, PDE6D, PDE8A, and PDE9A are highly expressed in both normal and adrenal tumor tissue, compared to other PDE family members." (PMID 32098292, 2020).
anorexia nervosa (1 paper, 2023). A disorder most often seen in adolescent females characterized by a refusal to maintain a minimally normal body weight, an intense fear of gaining weight, a disturbance in body image, and, in postmenarcheal females, the development of amenorrhea. "Furthermore, psychiatric disorders also had some causal effects on PDEs [obsessive–compulsive disorder on increased PDE6D and decreased PDE2A and PDE4D; anorexia nervosa on decreased PDE9A]." (PMID 37605207, 2023).
hepatocellular carcinoma (1 paper, 2019). A malignant tumor that arises from hepatocytes. "In this study, we newly showed that the delta subunit of rod-specific photoreceptor cGMP phosphodiesterase (PDE6D) contributes to hepatocellular carcinoma progression." (PMID 30901922, 2019). "However, the expression and specific function of PDE6D in hepatocellular carcinoma (HCC) were completely unknown." (PMID 30901922, 2019).
Hypertension (1 paper, 2022). The presence of chronic increased pressure in the systemic arterial system. "When taken together, these results suggest that site-specific inhibition of PDE2A and PDE6D at the outer mitochondrial membrane may provide a therapeutic target to ameliorate cardiac sympathetic impairment during the onset of hypertension." (PMID 35506379, 2022).
intrahepatic cholangiocarcinoma (1 paper, 2025). A carcinoma that arises from the intrahepatic bile duct epithelium in any site of the intrahepatic biliary tree. "Based on the training and validation cohorts of intrahepatic cholangiocarcinoma (ICA) bulk transcriptomes, seven metabolic enzymes were confirmed to be overexpressed in cases with poor prognosis: FH, MAT2B, PLOD2, PLOD1, PDE6D, ALDOC, and NT5DC3." (PMID 40034261, 2025). "Univariate logit binomial analysis, with the outcome being the proliferative subclass status of intrahepatic cholangiocarcinoma, confirmed the significance of the probes for seven enzymes: FH, MAT2B, PLOD2, PLOD1, PDE6D, ALDOC, and NT5DC3." (PMID 40034261, 2025).
leukemia (1 paper, 2022). A malignant (clonal) hematologic disorder, involving hematopoietic stem cells and characterized by the presence of primitive or atypical myeloid or lymphoid cells in the bone marrow and the blood. "In conclusion, we have validated the RAS chaperone PDE6D as a novel molecular target for aggressive leukemias." (PMID 35422065, 2022). "In summary, our study provides evidence that PDE6D-dependent RAS trafficking with downstream activation of PI3K/AKT and RAC constitutes a novel potential therapeutic target in high risk leukemias." (PMID 35422065, 2022). "First, we examined the antitumor effects of PDE6D inhibition on leukemia cell growth ex vivo by treating luciferase-expressing P12-ICHIKAWA cells with DW0254 before transplantation into sub-lethally irradiated non-obese diabetic severe combined immunodeficiency-gamma (NSG) mice." (PMID 35422065, 2022).
liver cancer (1 paper, 2019). An epithelial or non-epithelial malignant neoplasm that arises from the liver. "Together, PDE6D was found to be overexpressed in liver cancer and correlated with tumor stages, grading, and ERK activation." (PMID 30901922, 2019). "Moreover, datasets deriving from large-scale RNA profiling studies aimed at characterizing molecular classification schemes for diverse carcinomas revealed significant overexpression of PDE6D in liver cancer as compared to multiple other cancer types." (PMID 30901922, 2019). "However, the function of PDE6D in most cancer types remained elusive, and despite our study suggesting that interruption of the KRAS-PDE6D interaction in liver cancer might represent a novel therapeutic strategy, the expression and function of PDE6D in HCC was completely unknown." (PMID 30901922, 2019).
lung carcinoma (1 paper, 2022). "We examined the ratioof KRAS:PDE6D in three lung cancer cell linesthat had the highest KRAS levels among the cells analyzed (A549, H358,and H2009), as well as two cell lines with low KRAS levels but seeminglyhigher levels of PDE6D than KRAS (Daoy and Jurkat)." (PMID 35104933, 2022).
macular degeneration (1 paper, 2007). Loss of vision in the central portion of the retina (macula), secondary to retinal degeneration. "RPGRIP, RANBP2, NPM1, PDE6D, and NPHP5 were selected on the basis of protein interaction with RPGR or RPGRIP1 as these two proteins independently cause photoreceptor degeneration when mutated; ABCA4 was selected as a control gene, and because of its association with macular degeneration and RP." (PMID 17653054, 2007).
Onset (1 paper, 2025). The age group in which disease manifestations appear. "Variants in PDE6D (a gene encoding PDEδ) are linked to recessive Joubert syndrome (MIM: 615665), while knockdown of unc119c in zebrafish leads to visual impairment and early-onset retinal dystrophy." (PMID 40037334, 2025).
prostate carcinoma (1 paper, 2025). A carcinoma that arises from epithelial cells of the prostate gland. "A previous study revealed that metformin inhibits the progression of castration-resistant prostate cancer by modulating PDE6D-induced purine metabolic alterations and activating the cGMP/PKG pathway." (PMID 41001045, 2025).
cancer (7 papers, 2019 to 2025). A tumor composed of atypical neoplastic, often pleomorphic cells that invade other tissues. "Functionally, PDE6D depletion reduced cancer cell proliferation and migration, and conferred resistance to the chemotherapy drug sorafenib." (PMID 41179677, 2025). "We therefore continued with a 2D proliferation analysis for synergismin five KRAS mutant and dependent cancer cell lineswith diverse levels of PDE6D and PRKG2 dependencies." (PMID 38758695, 2024). "We found that KRAS and PDE6D relative levels are widelyvariable among different cell types, with the highest levels of bothproteins in human cancer cells (A549, H358, and H2009) and their lowestlevels in retinal retinal pigmented epithelial (RPE) cells." (PMID 35104933, 2022). "Meanwhile, studies by our and other groups suggested that targeting PDE6D-KRAS interaction is an effective approach to tackle both KRAS wild type and -mutated cancer types." (PMID 30901922, 2019). "Our resultssuggest reevaluating PDE6D as a K-Ras surrogate target in cancer." (PMID 38758695, 2024). "Moreover, this PDE6D interactome was significantly involved in major cancer-related transcription factor and cytoplasmatic signaling pathways including TGF-β and Smad signaling pathways." (PMID 30901922, 2019). "Moreover, PDE6D expression correlated significantly with KRAS expression levels in HCC tissues, which is in accordance with the finding that PDE6D serves as a novel targetable KRAS transport chaperon in cancer cells." (PMID 30901922, 2019). "However, despite these infrequent studies, the expression, precise function, and cellular localization of PDE6D in cancer including HCC, as well as its potential role in therapy resistance, remained unknown and were addressed in this study." (PMID 30901922, 2019). "Together with novel and specific highly-efficient small molecule inhibitors of the PDE6D-KRAS interaction, this marks a promising therapeutic strategy for HCC and other cancer types." (PMID 30901922, 2019). "The delta subunit of rod-specific photoreceptor cGMP phosphodiesterase (PDE6D) mediates antegrade trafficking of KRAS to the cell membrane implicating its potential crucial role in cancer." (PMID 30901922, 2019). "By contrast, Deltaflexin3 displayed the overallhighest selectivityfor PDE6D-dependent and KRAS mutant,as compared to HRAS mutant cancer cell lines, consistent with its K-RasG12V selectivity detectedby BRET and its off-target activity being lowest among the investigated compounds." (PMID 38758695, 2024). "In silico analysis was performed using the OncomineTM human cancer microarray database to determine PDE6D expression in HCC patient tissues compared to non-tumorous livers." (PMID 30901922, 2019). "Increased PDE6D levels in ICA may enhance tumor growth by modulating intracellular cyclic nucleotide levels, influencing pathways such as MAPK/ERK and PI3K/Akt, which are often dysregulated in cancer." (PMID 40034261, 2025). "Together, PDE6D might affect diverse cytoplasmatic and nuclear pathways in HCC and potentially also in other cancer types, which should be explored together with its strong potential as a novel therapeutic and diagnostic target in HCC progression and chemoresistance." (PMID 30901922, 2019). "Novel small molecule inhibitors (i.e., “deltarasin” and “deltazinone 1”), which bind to the prenyl-binding pocket of PDE6D, impair the enrichment of RAS proteins at the plasma membrane, thereby inhibiting RAS activation, which has been considered a desirable goal in cancer research for a long time." (PMID 30901922, 2019).
tumor (3 papers, 2019 to 2025). "Aiming at characterizing the potential prognostic and functional relevance of different cellular localization patterns of PDE6D, we found that cytoplasmatic PDE6D expression (compared with samples with “nuclear staining only”) was associated with enhanced tumor stages." (PMID 30901922, 2019). "Overexpression of PDE6D in HCC correlated with enhanced tumor stages, tumor grading, and ERK activation." (PMID 30901922, 2019). "Moreover, higher PDE6D expression correlated with enhanced tumor grading, tumor stages, and KRAS expression levels." (PMID 30901922, 2019). "Furthermore, our results showed a clear correlation of PDE6D expression and cellular localization with tumor grading, tumor stages, ERK activation, and KRAS activation." (PMID 30901922, 2019). "PDE6D localization patterns in human HCC tissues revealed that a cytoplasmatic PDE6D expression pattern was associated with enhanced membrane localization of KRAS (which resembles KRAS-activation), enhanced ERK-activation and advanced tumor stages." (PMID 30901922, 2019). "Accordingly, we found that PDE6D expression correlated with tumor grading and tumor stages." (PMID 30901922, 2019). "Moreover, PDE6D, as the delta subunit of rod-specific photoreceptor cGMP phosphodiesterase, is significantly overexpressed in hepatocellular carcinoma and correlates with advanced tumor stages and ERK activation." (PMID 41179677, 2025). "Quantitative RT-PCR analysis of paired tumor specimens and corresponding non-tumorous liver tissues revealed significant upregulation of PDE6D mRNA levels in HCC tissues (N = 15 pairs)." (PMID 30901922, 2019).
PDE6D also shares sentences with these, for which no sentence is quoted: breast tumor (1 paper); cone-rod dystrophy (1); infection (1); Joubert syndrome-22 (1); MORM syndrome (1); psychiatric disorder (1).